ALKBH5 (alkB homolog 5, RNA demethylase)
Diseases named in the same sentence as ALKBH5 in open-access papers (continued):
Sharing a sentence is not in itself a finding about the gene and the disease.
glioblastoma (continued). "Since the results in GBMSCs showed that ALKBH5 could regulate CHK1 expression, we then analyzed the correlation between ALKBH5 and CHK1 expression using the glioblastoma database of the Cancer Genome Atlas (TCGA)." (PMID 33375621, 2020). "ALKBH5 is required for GSC self-renewal and predicts poor survival of glioblastoma patients." (PMID 30149601, 2018). "Immunostaining analysis of primary glioblastoma samples showed that cells overexpressing ALKB5 are characterized by the expression of the glioma stem cell markers SOX2, Nanog, Nestin, and OCT4; this stem cell phenotype is rescued by ALKBH5 expression." (PMID 30279357, 2018). "ALKBH5 was highly expressed in various cancers, including non-small-cell lung cancer, glioblastoma (GBM), hepatocellular carcinoma, colorectal cancer, gastric cancer, endometrial cancer, and breast cancer, with high expression of ALKBH5 being closely related to the malignancy of these tumors." (PMID 40001461, 2025). "In addition, a novel inhibitor of ALKBH5, named TD19, has been identified to irreversibly modify residues C100 and C267, thus preventing ALKBH5 from binding to m6A-containing RNA and displays promising anti-cancer efficacy in AML and glioblastoma multiforme cell lines." (PMID 40958857, 2025). "ALKBH5 overexpression induces immunosuppressive TME and promotes immune evasion in multiple cancers, including ICC, melanoma, colorectal carcinoma and glioblastoma multiforme, suggesting that ALKBH5 could affect tumor response to immunotherapy." (PMID 35063010, 2022). "In addition, ALKBH5 was also involved in kinds of cancers or non-cancers, such as glioblastoma, pancreatic cancer, colon cancer, breast cancer, gastric cancer, lung cancer, ovarian cancer, diabetes and reproductive system diseases." (PMID 32742194, 2020). "Moreover, ALKBH5 mRNA expression resulted as a negative prognostic factor for glioblastoma patients, whereby a low ALKBH5 mRNA expression correlated with a longer overall survival." (PMID 32316617, 2020). "Furthermore, lncRNA FOXM1-AS could accelerate the mutual effect of ALKBH5 and FOXM1 nascent transcripts and conduce to the maintenance of glioblastoma stem cells." (PMID 32793593, 2020). "In the context of glioblastoma (GBM), the m6A demethylases FTO and ALKBH5 have also been reported to act as oncogenes." (PMID 32111216, 2020). "Specifically, ALKBH5 is a critical regulator in the development of several cancers, including thyroid cancer, hypopharyngeal carcinoma, non-small cell lung cancer (NSCLC), and glioblastoma (GBM)." (PMID 40271153, 2025). "Recently, a study has demonstrated that the m6A demethylase ALKBH5 served as a negative prognostic biomarker for GBM patients and maintained the tumorigenicity of glioblastoma stem cell–like cells by activating FOXM1 expression and cell growth." (PMID 34150845, 2021). "Since ALKBH5 is clearly overexpressed in GBMSC, we focused our study on this m6A RNA demethylase and tested whether the overexpression of ALKBH5 observed in GBMSC derived from human glioblastoma biopsy specimens has a functional role in mediating resistance to radiotherapy and invasion." (PMID 33375621, 2020).
breast cancer (147 papers, 2016 to 2025). A primary or metastatic malignant neoplasm involving the breast. "Analysis of breast cancer clinical samples from the TCGA database demonstrated a positive association between HIF1α and ALKBH5 mRNA expression." (PMID 38520019, 2024). "In contrast, hypoxia induces m6A-demethylation of NANOG mRNA in a HIF- and ALKBH5-dependent manner to cause breast cancer stem cell phenotype." (PMID 34491904, 2021). "Alkylation repair homolog protein 5 (ALKBH5) is also associated with pancreatic cancer, gastric cancer and breast cancer." (PMID 34187307, 2021). "Semenza and colleagues showed that hypoxia was associated with increased breast cancer stem cell formation and elevated levels of ALKBH5 in breast cancer." (PMID 28081722, 2017). "Researchers have also found single-nucleotide polymorphisms (SNPs) in FTO and ALKBH5, which may have important roles in breast cancer, melanoma, pancreatic cancer and endometrial cancer." (PMID 34895230, 2021). "Numerous studies have demonstrated that m6A regulatory factors, including METTL3, METTL14, and ALKBH5, play pivotal roles in breast cancer cells, affecting cell proliferation, metastasis, and drug resistance." (PMID 39972939, 2025). "ENO can be modulated by m6A modifiers, including METTL3, KIAA1429, WTAP, YTHDF2 and ALKBH5, mediating the cell glycolysis process in lung adenocarcinoma, breast cancer and ovarian cancer." (PMID 41373022, 2025). "ALKBH5 drives glycolysis in resistant breast cancer cells by mediating YTHDF2-dependent m6A demethylation of GLUT4 mRNA, which stabilizes the transcript and enhances glucose metabolism." (PMID 40986143, 2025). "For example, overexpression of METTL3 enhances cell proliferation and resistance to chemotherapy, while ALKBH5-driven demethylation of pluripotency genes promotes breast cancer stemness." (PMID 41373981, 2025). "Currently, it has been discovered that the downregulation of ALKBH5 results in an elevation of m6A modification in breast cancer cells, thereby fostering the proliferation and migration of tumor cells." (PMID 39972939, 2025). "Hypoxia increases NANOG mRNA and protein expression through a HIF- and ALKBH5-dependent mechanism, increasing the proportion of breast cancer stem cell (BCSC) phenotypes." (PMID 39192357, 2024). "For instance, in gastric, colon, and breast cancers, ALKBH5 promotes tumorigenesis, whereas in esophageal, hepatocellular carcinoma, osteosarcoma, ALKBH5 reduces cancer malignancy." (PMID 38252669, 2024). "HIF-dependent ALKBH5 expression mediates the enrichment of breast cancer stem cells (BCSCs) in the hypoxic tumor microenvironment." (PMID 39192357, 2024). "In breast cancer cells ALKBH5 overexpression erases m6A methylation from the GLUT4 mRNA, protecting it from YTHDF2‐mediated degradation and increases its expression through stabilizing the transcript." (PMID 39661414, 2024). "Hypoxia-inducible factor (HIF)-1α and HIF-2α upregulate ALKBH5 expression in breast cancer cells under hypoxic conditions." (PMID 39192357, 2024). "Corroborating previous studies, ALKBH5, recognized as a prominent m6A demethylase, has been identified as a key player in a diverse array of cancers, such as breast carcinoma, stomach carcinoma, and colorectal carcinoma." (PMID 38501918, 2024). "High expression of ALKBH5 has been observed in breast cancer tissues from human epidermal growth factor receptor 2 (HER2)-therapy resistant patients." (PMID 37055798, 2023). "ALKBH5 is upregulated in breast cancer, glioma, lung cancer, ovarian carcinoma, gastric cancer and colon cancer, and knockdown of ALKBH5 inhibits cancer cells viability, colony formation and migration 7-12." (PMID 37325047, 2023). "Regarding the ALKBH5 m6A eraser, exposure to hypoxia induced the HIF-1α and HIF-2α-dependent expression of ALKBH5 that demethylates and stabilizes Nanog mRNA, leading to the acquisition of a cancer stem cell phenotype in breast cancer cells." (PMID 37369946, 2023).
breast cancer (continued). "A further study has demonstrated hypoxia-induced ALKBH5 upregulation in breast cancer, with the knockdown of ALKBH5 reducing tumour initiation, potentially demonstrating a conserved mechanism by which m6A contributes to tumour microenvironmental adaptation." (PMID 37444417, 2023). "Overexpression of ALKBH5 was found in breast cancer research to enhance the enrichment of breast cancer stem cells (BCSC)." (PMID 37519297, 2023). "Recently, ALKBH5 was shown to be directly targeted by HIF1α and regulated by HIF2α in breast cancer cells." (PMID 37149664, 2023). "Knockdown of ALKBH5 in MDA-MB-231 cells significantly weakens their capacity for tumor initiation due to the reduced breast cancer stem cells." (PMID 36551544, 2022). "Silencing of METTL14 and ALKBH5 significantly inhibited breast cancer cell growth and invasive activity." (PMID 36446846, 2022). "Previous studies have reported that METTL14 forms a negative feedback loop with ALKBH5/TFEB in cardiomyocytes treated with hypoxia/reoxygenation and constitutes a positive one with ALKBH5/HuR in breast cancer." (PMID 36288387, 2022). "To date, METTL3, ALKBH5, FTO, and YTHDF2 have been implicated in promoting breast cancer tumorigenesis by affecting cancer cell survival/proliferation and cancer stem cell pluripotency 23-26." (PMID 35966596, 2022). "For example, ALKBH5 is overexpressed and plays an oncogenic role in many tumors, such as breast cancer, Glioma and AML." (PMID 35063010, 2022). "The depleting of ALKBH5 reversed the pluripotency of breast cancer by inhibiting Nanog under hypoxic condition." (PMID 35721510, 2022). "Through our research, almost all of them were differentially expressed in breast cancer samples except ALKBH5." (PMID 35980268, 2022). "Later, it was demonstrated in human breast cancer cells that ALKBH5 is significantly upregulated under hypoxic conditions, while knockdown of HIF-1α and/or HIF-2α abrogates this effect." (PMID 35063010, 2022). "Knockdown of ALKBH5 inhibits breast cancer cell viability, colony formation and migration, confirming the oncogenic properties of ALKBH5 in this malignancy." (PMID 35063010, 2022). "Hypoxia induces ALKBH5 expression in breast cancer cells, which reduces the m6A modification of NANOG and promotes the initiation and metastasis of breast cancer." (PMID 36536402, 2022). "N6-methyladenosine (m6A) is the most abundant internal modification implicated in tumorigenesis; the m6A demethylase, a-ketoglutarate-dependent dioxygenase AlkB homolog 5 (ALKBH5), has demonstrated the promoting function in the development of breast cancer." (PMID 36551544, 2022). "Reducing m6A expression by the knockdown of ALKBH5 is capable of inhibiting the viability, colony formation and cell migration of breast cancer cells, thus arresting the tumorigenesis of breast cancer." (PMID 36551544, 2022). "ALKBH5 has been shown to regulate various biological and pathophysiological processes including: meiosis, gametogenesis, autophagy, glioblastoma, breast cancer, lung cancer and infertility." (PMID 35552718, 2022). "ALKBH5-mediated m6A-demethylation of NANOG mRNA is involved in hypoxia-induced breast cancer stem cell phenotype." (PMID 35595748, 2022). "Later, these authors found another pluripotency factor, KLF4, is also positively regulated by ALKBH5-mediated m6A methylation in breast cancer, contributing to the overall regulation of the BCSC phenotype by ALKBH5." (PMID 35063010, 2022). "Knockout of ALKBH5 in MDA-MB-231 breast cancer cells remarkably reduced breast-to-lung metastasis in immunodeficient mice." (PMID 34745269, 2021). "Another study on ALKBH5 found that the exposure of breast cancer cells to hypoxia significantly increased the expression of ALKBH5 in tissues and cells." (PMID 34211849, 2021). "In breast cancer, ALKBH5 has been shown to promote tumourigenesis by decreasing adenosine methylation in KLF4 and NANOG mRNAs, enhancing their stability in breast cancer stem cells." (PMID 33461542, 2021).
breast cancer (continued). "Recently, it was reported that ALKBH5 functions as a tumour promoter in the pathogenesis of breast cancer." (PMID 34044876, 2021). "In MDA-MB-231 cells, the knockdown of ALKBH5 significantly reduced the number of breast cancer stem cells." (PMID 34044876, 2021). "Methyltransferase METTL3 can enhance AK4 expression, increase the level of ROS in breast cancer cells and activate p38 Kinase, and promote the resistance of breast cancer to Tamoxifen, and the role of demethylation ALKBH5 is opposite to that of METTL3." (PMID 34484567, 2021). "The expressions of hypoxia-induced pluripotent factors and ALKBH5 or ZNF217 in breast cancer cell lines are dependent on HIF." (PMID 34745269, 2021). "The ALKBH5 protein maintains the stem cell characteristics and inhibits their differentiation ability in breast cancer." (PMID 33314339, 2021). "By knocking-down ALKBH5 the oncogenesis in breast cancer can be altered through a lower number of BCSC." (PMID 33430133, 2021). "ALKBH5 affects the tumorigenicity of human breast cancer cells and the spermatogenesis and fertility of mice." (PMID 34211849, 2021). "Through METTL14 overexpression or ALKBH5 knockdown experiments, some researchers have found that increasing global m6A levels impede propagation of human breast cancer cells." (PMID 34895230, 2021). "In breast cancer, ALKBH5 is a direct target of hypoxia-inducible factor 1α (HIF-1α) and HIF-2α and regulates breast cancer stem cell phenotype by downregulating the m6A modification on Nanog mRNA methylation." (PMID 33428593, 2021). "In breast cancer, hypoxia facilitates expression of ALKBH5, resulting in reduction of NANOG mRNA m6A level and enhancement of mRNA stabilization." (PMID 34363020, 2021). "ALKBH5 upregulation showed decreased m6A level in pluripotency induction marker NANOG mRNA in breast cancer stem cells (BCSCs)." (PMID 32194861, 2020). "Similar result was also observed in breast cancer cells where ALKBH5-mediated m6A demethylation of NANOG mRNA enhanced the breast cancer stem cell (BCSC) in hypoxic condition." (PMID 32194861, 2020). "In breast cancer, overexpression of ALKBH5 promotes mRNA stability and expression of the pluripotency factor NANOG, which is required for primary tumor formation, and metastasis by catalyzing m6A demethylation." (PMID 32709063, 2020). "On the one hand, ALKBH5 was up-regulated in kinds of cancer tissues and cell lines, such as breast cancer, lung cancer and epithelial ovarian cancer, and played an oncogenic role in tumor progression." (PMID 32742194, 2020). "In breast cancer, ALKBH5 mediates the m6A-demethylation of mRNA, inducing the breast cancer stem cell phenotype." (PMID 32258108, 2020). "The ALKBH5 plays an important role in controlling breast cancer progression through the HIF-ALKBH5-dependent pathway." (PMID 33511112, 2020). "Till now, a few of studies have shown aberrant expression of five m6A regulators in breast cancer and clarified the molecular mechanism of ALKBH5- and ZNF217-mediated tumor occurrence." (PMID 33585234, 2020). "Some articles have demonstrated the role of ALKBH5 in various cancers, such as pancreatic cancer, breast cancer, and gastric cancer." (PMID 33237039, 2020). "Hypoxia-inducible factor (HIF)-1α-and HIF-2α-dependent ALKBH5 in breast cancer cells can be stimulated under hypoxia condition, leading to demethylation of NANOG mRNA." (PMID 33362863, 2020). "Up to date, the expression of ALKBH5 was up-regulated or down-regulated in various cancers, and played an oncogenic or tumor suppressive role in breast cancer, gastric cancer, colon cancer and so on." (PMID 32742194, 2020). "ALKBH5 promoted cancer cell renewal and growth in breast cancer by removing m6A from NANOG mRNA, which in turn enhanced NANOG mRNA stability and pluripotency of cancer cells." (PMID 32111213, 2020).
breast cancer (continued). "HIFs mediate adaptive metabolic responses and mitochondrial ROS production in breast cancer tumour stem cells (BCSCs), enhancing the CSC phenotype via ITGA6 and promoting ALKBH5 expression, which plays a critical role in tumour-initiating breast cancer cells." (PMID 32913192, 2020). "For example, in human breast cancer cells, knockdown ALKBH5 contributed to significantly decrease the number of cancer stem cells and the opportunity of tumorigenesis." (PMID 32682400, 2020). "In this study, by analyzing the prognostic role of m6A modulators (METTL3, METTL14, WTAP, FTO, and ALKBH5) in breast cancer using on-line databases, we found that only METTL3 played an important role in TNBC metastasis." (PMID 32766145, 2020). "The up-regulated ALKBH5 caused by hypoxia, decreases the m6A methylation of NANOG mRNA and promotes its expression, finally leading to the power of breast cancer stem cells (BCSCs)." (PMID 32612834, 2020). "ALKBH5 promoted breast cancer stem cell (BCSC) specification and enrichment in the tumor microenvironment though catalyzing the demethylation of an adenosine residue in the 3′-UTR of NANOG mRNA." (PMID 32742194, 2020). "We will discuss the different roles of ALKBH5 in various cancers thereinafter, including breast cancer, lung cancer, pancreatic cancer, glioma and so on." (PMID 32742194, 2020). "In breast cancer cells, the m6A demethylase, ALKBH5, reduced the level of m6A modification in NANOG mRNA, which subsequently stabilized NANOG mRNA and thus promoted breast cancer stem cell phenotypes." (PMID 32101138, 2020). "Zhang C et al55 found that ALKBH5 enhances m6A stability, which increases the levev of m6A in breast carcinoma." (PMID 32742465, 2020). "While we shed light on the epigenetic regulation by FTO in breast cancer, ALKBH5, another m6A demethylase, was previously reported to affect breast cancer stemness phenotype in hypoxia." (PMID 30922314, 2019). "A study showed that hypoxia was related to increased breast cancer stem cell formation directly through upregulating ALKBH5 or indirectly through ZNF217/METTL3-METTL14-complex pathway." (PMID 30877265, 2019). "Hypoxia-induced ALKBH5 expression in breast cancer cells enhances mRNA stability of homeobox transcription factor NANOG and induces its overexpression, leading to a phenotype specific to breast cancer stem cells." (PMID 30654440, 2019). "For instance, the m6A demethylase ALKBH5 was reported to induce the breast cancer stem cell phenotype by demethylating NANOG mRNA, whereas a later study revealed an important role of ALKBH5 in inhibiting the progression of pancreatic cancer." (PMID 31607270, 2019). "IHC staining data from HPA database showed a predominant upregulation of ALKBH5 but downregulation of FTO in breast carcinoma tissues in comparison with normal breast tissues." (PMID 31632489, 2019). "Our findings differ from previous reports that have shown total RNA m6A levels in breast cancer cell lines decrease in hypoxia conditions through HIF mediated induction of the demethylase ALKBH5 and/or METTL3 sequestration by ZNF217." (PMID 30131850, 2018). "Exposure of breast cancer cells to hypoxia promotes the ALKBH5-mediated demethylation of m6A in NANOG transcripts, consequently enhancing NANOG expression." (PMID 29439529, 2018). "ALKBH5 is highly expressed in lung cancer (GENT database) and hypoxia activates ALKBH5 in breast cancer cells." (PMID 29904125, 2018). "Previous reports using breast cancer stem cells have shown that hypoxic activation of HIF led to decreased RNA methylation through HIF-mediated induction of the demethylase ALKBH5 and METTL3 suppressor ZNF217." (PMID 30131850, 2018). "ALKBH5 and m6A depletion was reported to induce breast cancer via ALKBH5-mediated NANOG mRNA demethylation." (PMID 29423080, 2018).